CTLA4 (cytotoxic T-lymphocyte associated protein 4)
Diseases named in the same sentence as CTLA4 in open-access papers (continued):
Sharing a sentence is not in itself a finding about the gene and the disease.
tumor (continued). "In the therapy group, a significant decrease of tumour perfusion (WiAUC) was observed following the one-week treatment course with combined anti-PD-L1/anti-CTLA-4 immunotherapy (23767 ± 16937 a.u. at baseline to 8054 ± 10083 a.u. at follow-up; p = 0.008)." (PMID 40591551, 2025). "ACT can be used in combination with immune checkpoint inhibitors (such as PD-1, PD-L1, or CTLA-4 inhibitors) to relieve the suppression of T cell functions and further enhance the anti-tumor immune response." (PMID 40094019, 2025). "Immune checkpoint blockade (ICB) exemplifies this approach by employing antibodies to target inhibitory receptors such as PD-1 and CTLA-4 on T cells and PD-L1 on tumors, thereby preventing tumor-driven suppression of T cell activity." (PMID 41294574, 2025). "Tumor cells expressing CD80/86 can induce the translocation of CTLA4 from the cytoplasm to the cell surface in tumor-infiltrating lymphocytes, resulting in the suppression of T lymphocyte activity." (PMID 39941803, 2025). "Distribution of quantitative whole tumour PD‐L1, PD‐1 and CTLA‐4 in situ RNAscope expression (estimated dot/cell) with respect to relative ACD semi‐quantitative scores in neoplastic cells (Wilcoxon's rank‐sum test)." (PMID 39789732, 2025). "In agreement with the transcriptomic changes, RIT induced tumor growth delay and prolonged survival (36 days vs. 23 days in the control group, p < 0.01), and synergized with anti-CTLA4 and anti-PD-1 therapy (median survival >65 days, p < 0.001, vs. RIT alone)." (PMID 41022704, 2025). "Cadonilimab is a humanized bsAb that binds concurrently to PD-1 and CTLA-4 with high affinity on tumor-infiltrating lymphocytes (TILs), thereby enhancing antitumor efficacy and also safety." (PMID 40075753, 2025). "Despite this, the functionality of these T cells is inhibited by the PD-1/PD-L1 axis (PD-L1 expressed by tumor cells) and CTLA-4 signaling (expressed by T cells), alongside immune suppressors within the microenvironment." (PMID 40260289, 2025). "By simultaneously targeting multiple immune checkpoints, such as PD-1/PD-L1 and CTLA-4, this approach overcomes the limitations of single-target therapies and amplifies anti-tumor immune responses." (PMID 40356928, 2025). "ICIs such as ipilimumab (anti-CTLA-4) and nivolumab (anti-PD-1) act by reversing T-cell inhibition, thereby enhancing anti-tumor immunity." (PMID 41246725, 2025). "We further evaluated the correlation between CTLA4 expression and other markers of tumor inflammation." (PMID 40523912, 2025). "Considering the immunosuppressive roles of Treg cells, the administration of anti-CTLA-4 antibody into mice with Hepa1-6 KO tumors yielded slight influences on tumor growth." (PMID 40139191, 2025). "Regulatory T cells (Tregs) and T follicular regulatory (Tfr) cells have been studied in relation to PD-1 and Cytotoxic T-Lymphocyte Associated protein 4 (CTLA-4), using human tumor samples, syngeneic mouse models, and tumor cell lines." (PMID 38534769, 2024). "The use of ICB in tumor immunotherapy has been found to enhance antitumor T‐cell responses through anti‐PD‐1, anti‐CTLA‐4, or anti‐PD‐L1 therapy." (PMID 38938284, 2024). "ICOS+ Th1-like cells play a crucial role in the antitumor effect of anti-CTLA-4 therapy, constituting the majority of tumor-specific, IFN-γ producing CD4 T cells." (PMID 38517331, 2024). "Currently, the most prevalent immune checkpoint blockade approach in clinical tumor immunotherapy involves the use of anti-CTLA-4 or anti-PD-1/PD-L1 antibodies, either individually or in combination." (PMID 39456702, 2024). "In a study of experimental A20 tumor models, US-activated CTLA-4 and PD-L1 antibodies were successfully activated in situ, leading to significant suppression of tumor growth." (PMID 39239514, 2024). "Expression of these co-inhibitory receptors results in increased tumor tolerance and T cell anergy through pathways parallel to the canonical PD-1/PD-L1 and CTLA-4/CD80/86 axes." (PMID 39105820, 2024).
tumor (continued). "For muscle-invasive BC and metastatic stages, immune checkpoint inhibitors targeting CTLA-4, PD-1, and PD-L1 have emerged as potent therapies, enhancing immune surveillance and tumor cell elimination." (PMID 39682686, 2024). "ICB enhances the immune system’s ability to attack tumor cells by inhibiting immune checkpoint molecules, such as PD-1, PD-L1, and CTL-associated protein-4 (CTLA-4), and by reducing T-cell inhibition within the TME." (PMID 39840050, 2024). "Although anti-CTLA-4 mAB effectively promotes tumor regression in some malignancies, it is insufficient in BC." (PMID 38956700, 2024). "Given the significance of CTLA-4 for autoimmunity and anti-tumor immunotherapy, the precise pathways responsible for its function still need to be determined." (PMID 38180994, 2024). "Although we did not see an increase in LAG-3 or TIM-3 expression with nivolumab, we found a striking increase in CTLA-4 expression on tumor-infiltrating CD8+ T cells." (PMID 38228729, 2024). "Our data further demonstrated that PD-L1 and anti-CTLA4 combined with RT significantly inhibited tumor growth." (PMID 39877375, 2024). "The presence of tumour‐infiltrating lymphocytes (TILs) and the expression of immune checkpoint molecules such as PD‐1 and CTLA‐4, as well as those key secretory factors, are indicative of the immune landscape within TC tumours." (PMID 39163517, 2024). "Cytometric analyses have further revealed the upregulation of immunotherapeutic targets, such as CTLA-4, in tumor-infiltrating T-cells." (PMID 39684701, 2024). "CTLA4+ T cells play a key role in immune escape in HCC, as evidenced by the fact that they are highly expressed in tumor tissues and associated with poor prognosis." (PMID 38604154, 2024). "By genetically modifying the tumor-soluble bovine pox virus to express IL-7 and IL-12, it is possible to enhance the sensitivity of anti-PD-1 and CTLA4 antibody therapy." (PMID 39055561, 2024). "Later it was appreciated that both anti-self and anti-tumor immunity are regulated by shared mechanisms, including the PD-1 and CTLA-4 immune checkpoint pathways." (PMID 38443917, 2024). "For example, cytotoxic T lymphocyte antigen 4 (CTLA4) plays an important regulatory role in the functional state of the regulatory T-cell; thus, it is involved in the formation of the tumor suppressive immune microenvironment." (PMID 38552216, 2024). "Combining therapies targeting both PD-1/PD-L1 and CTLA-4 has shown synergistic effects in certain cancers, leading to enhanced anti-tumor responses compared to monotherapy." (PMID 38315450, 2024). "In the CT26 mouse model of CRC, immune checkpoint inhibition via anti-CTLA-4 increased Arg1 expression in the tumour microenvironment." (PMID 38464388, 2024). "Although numerous immune checkpoint inhibitors, such as CTLA-4, PD-L1, and PD-1 inhibitors, have been introduced to the market, the majority of tumor patients will experience tumor recurrence, metastasis, and drug resistance." (PMID 39575257, 2024). "PAD4 inhibitors are able to inhibit the expression of genes, such as PD1 and LAG3, which are potential immune checkpoint inhibitors, and their ability to inhibit tumor progression can be enhanced in combination with anti-CTLA-4 and anti-PD-1 antibodies." (PMID 38543229, 2024). "We performed 1x8 Gy of the primary tumor ± anti-CTLA4 or anti-PD1, and ± daily oral application of ABx or metabolites." (PMID 38500667, 2024). "Inhibitory signals from the PD-1/PD-L1 axis and CTLA-4 can hinder T-cell immune responses, preventing the elimination of tumor cells and potentially promoting tumor growth." (PMID 39902127, 2024). "As a potential key molecule for the anti-tumor effect following anti-CTLA-4 therapy, ICOS exhibited a fourfold change in expression between Cluster 1 and Cluster 2 in our study." (PMID 39623397, 2024).
tumor (continued). "Immune checkpoints are regulatory molecules in the immune system, with the PD-1/PD-L1 and CTLA-4 pathways emerging as significant contributors to tumor immunosuppression." (PMID 39290709, 2024). "BCP-84 and BCP-85 showed higher tumor inhibition efficacy over either of anti-PD-L1 or anti-CTLA-4 monotherapy in C57BL/6CTLA-4 knock-in mice bearing a colorectal MC38 tumor." (PMID 38257366, 2024). "This downregulation of the immune response via the CTLA-4 pathway inhibits the activation of T cells and can lead to a decrease in their ability to recognize tumor cells and antigens." (PMID 38893164, 2024). "This distinct expression pattern suggests that B7-H4 holds greater tumor specificity and sensitivity compared to PD-1 and CTLA-4, rendering it a promising emerging target for tumor therapy." (PMID 39267740, 2024). "Tumor-suppressor miRNAs play a role in controlling the antitumor immune response by regulating immune checkpoints such as PD-1, PD-L1, and CTLA-4." (PMID 38462628, 2024). "Overexpression of CTLA4 on regulatory T cells (Tregs) within the tumor micro-environment impairs the function of effector T cells, leading to immune tolerance and tumor progression." (PMID 39336572, 2024). "The data showed that the CTLA4 level was reduced in the Foxp1-deleted tumor model compared to the wild-type tumor model." (PMID 38398223, 2024). "Monoclonal antibodies targeting CTLA-4, such as ipilimumab, disrupt this inhibitory signal, enhancing T cell activation and anti-tumor immune responses." (PMID 39161771, 2024). "The recent advancements in targeting immune checkpoint molecules, including PD-1, PD-L1, and CTLA4, have indicated that the suppression of tumor-specific immunity plays a crucial role in the pathology of HNSCC18." (PMID 38225277, 2024). "Popular ICIs include anti-PD-1, anti-PD-L1, and anti-CTLA4 agents; however, it is important to determine which mechanism confers maximum tumor killing when administered in tandem with radiotherapy." (PMID 39124563, 2024). "We found improved an anti-tumor response consisting of a significantly prolonged tumor growth delay, and in some instances, a durable complete resolution of tumors, with the combination treatment of IR and anti-CTLA4." (PMID 39199612, 2024). "Patients with these mutational markers exhibit a higher tumor mutational burden (TMB), a well-established marker correlated with improved survival in NSCLC patients treated with PD-1 plus CTLA-4 blockade." (PMID 38951894, 2024). "Ipilimumab works by blocking the binding of CTLA-4 to the B7 ligand, ensuring the activation and proliferation of T cells, ultimately leading to its anti-tumor effect." (PMID 38294629, 2024). "To further validate the efficacy of combined RT and immunotherapy in tumor treatment, we incorporated two ICIs, anti-PD-L1 and anti-CTLA4, with RT in the 20 + 6 Gy group." (PMID 39877375, 2024). "Tumor mutational burden (TMB) is another well-studied potential biomarker, that predicts the efficacy of immunotherapies, such as PD-1 and CTLA-4 inhibitors, across a spectrum of cancers." (PMID 38629578, 2024). "Cytotoxic T-lymphocyte-associated protein 4 (CTLA-4) and programmed death receptor 1 (PD-1) have been demonstrated to be key regulators of T-cell anti-tumour immune response and are effective targets for immunotherapeutic agents." (PMID 39001359, 2024). "Targeting CTLA-4 limits the priming of naïve T cells; however, it also attenuates direct anti-tumor T-cell activity in the effector phase, in parts, by decreasing suppressive Tregs." (PMID 38893220, 2024). "Inhibitory checkpoint molecules, such as CTLA-4, programmed cell death protein-1 (PD-1), and programmed cell death ligand 1 (PD-L1), can suppress anti-tumor immune responses in solid tumors." (PMID 39684424, 2024). "Further, neoAg SLP vax used in combination with anti-CTLA-4 or anti-PD-1 provided superior tumor growth inhibition compared to combination anti-CTLA-4 and anti-PD-1." (PMID 39446585, 2024).
tumor (continued). "Preclinical studies have demonstrated upregulated expressions of LAG-3 or TIM-3 in immunotherapy-resistant tumors, whilst co-blockade of these checkpoint molecules augments tumor response to anti-CTLA-4 and anti-PD-1 immunotherapies." (PMID 38673829, 2024). "In this report we show that even without tumor debulking, CRI (a combination of RT, srIL-2, IL-12 and anti- CTLA-4), can induce complete regressions of some late-stage tumors with tumor volumes of 2000 mm3 or larger." (PMID 39076988, 2024). "IPS can quantify the determinants of tumor immunogenicity and has predictive value in cancer patients treated with CTLA-4 and PD-1 blockers." (PMID 38977952, 2024). "Both CTLA-4 and PD-1 are expressed in exhausted T cells, suggesting that soluble ICMs originate from tumor-infiltrating exhausted T cells." (PMID 38987362, 2024). "To understand the kinetics of antitumor immune response, we longitudinally imaged mice with intracranial GBM tumors during anti-PD-1/CTLA-4 therapy, tracking tumor growth with bioluminescent imaging." (PMID 38951146, 2024). "Mounting evidence suggests that the dual blockade of PD-1/PD-L1 and CTLA-4 exhibits stronger anti-tumor activity in certain cancer types." (PMID 38762484, 2024). "The tumor specimens obtained from these individuals were expected to demonstrate positive immunological reactions in relation to PD-1/PD-L1 inhibitors, CTLA4 inhibitors, or a combination of both therapeutic interventions." (PMID 38240703, 2024). "Following successful CD8 and NK cell depletion, the delayed tumor growth conferred by anti-CTLA-4 and anti-TIGIT therapies was partially lost, suggesting that these responses are mediated by both CTLs and NK cells." (PMID 38914547, 2024). "Tumor cells express immune checkpoints such as PD-L1 and CTLA4, which bind on T cells, inhibiting their activity." (PMID 39201585, 2024). "By blocking CTLA-4, these inhibitors enhance T cell responses to tumor cells, thereby potentially enhancing antitumor immunity." (PMID 39493764, 2024). "Kaplan-Meier analysis showed that the coexpression of the VISTA+/CTLA4+/PDL1+ and VISTA+/CTLA4+/PD1+ checkpoints on tumor cells (TCs)were associated with OS (p=0.02 and p<0.001; respectively)." (PMID 38634058, 2024). "Altogether, our results indicated a well-tolerated anti-tumor effect using high-dose radiation combined with anti-CTLA4 in radiation-recurrent PCa, with a one-third cure rate." (PMID 39199612, 2024). "The tumor growth in the combination of IL-12 and CTLA-4 blockade group were complete remission in most mice, compared with the IL-12 or anti–CTLA-4 conferred only a minor or no survival advantage respectively." (PMID 38753073, 2024). "We previously reported enhanced antitumor activity when APR-246 was combined with either anti-PD-1 alone or dual blockade of PD-1 and cytotoxic T-lymphocyte antigen 4 protein (CTLA-4) in multiple murine tumor types." (PMID 37891002, 2024). "Given the immunological effects achieved by isoform-specific targeting of sCTLA-4, it is feasible that the anti-tumor activity of conventional pan-CTLA-4 antibodies occurs at least in part through blockade of sCTLA-4." (PMID 38053333, 2024). "The creation of potential liposomes altered with anti-CTLA-4 Nb and RGD to function as a fresh CTLA-4 molecule blocker with tumor targeting is first covered in this paper." (PMID 38824143, 2024). "A study revealed that the increased expression of Ly6K/E promotes cytokine-induced immune checkpoint molecules PDL1 and CTLA4 expression, enhances tumor-infiltrating T regulatory cells, and reduces natural killer cell activation." (PMID 39727968, 2024). "By preventing the CD28-B7 engagement, CTLA-4 hinders the co-stimulatory signaling and suppresses T-cell-mediated anti-tumor immune responses." (PMID 38064127, 2024). "Nivolumab increases CTLA-4 expression in the primary tumor, and subsequent nephrectomy increases circulating concentrations of sPD-L1, sPD-L3 (sB7-H3), and s4-1BB." (PMID 38228729, 2024).
tumor (continued). "Therapeutic blockade of CTLA4 is achieved with immune inhibitors of CTLA4, such as the antibody ipilimumab, which can restore anti-tumor activity to cytotoxic T lymphocytes." (PMID 38715617, 2024). "In sharp contrast, mice treated with NU-SL40 and anti–PD-1/–CTLA-4 exhibited tumor regression in all mice." (PMID 39436696, 2024). "Tumor tissues treated with anti-CTLA-4 also increased gene expression of sEH compared to vehicle-treated tumor tissue." (PMID 38330013, 2024). "The combination of CTLA-4 and PD-1 blockers has been proposed to have a synergistic effect on activating anti-tumor immune responses, leading to increased response rates in patients." (PMID 38375475, 2024). "Tremelimumab, a human immunoglobulin G2 mAb that binds selectively to CTLA-4, has shown an acceptable safety profile and clinical activity across several tumor types." (PMID 39043009, 2024). "The CheckMate 648 trial further demonstrated the potential of dual immunotherapy targeting both programmed death ligand-1 (PD-L1) and cytotoxic T lymphocyte-associated protein 4 (CTLA-4) in advanced ESCC, as well as in other neoplasms." (PMID 39105827, 2024). "A combination therapy using anti PD-1 antibody Nivolumab and anti CTLA-4 antibody ipilimumab resulted in tumor remission in 29% of patients with HCC within 6 weeks of treatment." (PMID 38571964, 2024). "The suppression of the activity of the cells by inhibition of CTLA-4 has been shown to have prominent anti-tumor and anti-autoimmune effects, but it also resulted in high toxicity to the non-cancerous cells." (PMID 39727496, 2024). "The rationale behind our aptamer design is rooted in the documented effectiveness of targeting NKG2A and CTLA4 for bolstering anti-tumor immunity." (PMID 38473398, 2024). "CTLA-4 inhibitors hinder the transmission of inhibitory signals from CTLA-4 to cells, stimulating the proliferation of T cells that target tumor antigens and strengthen the immune system’s ability to eliminate tumor cells." (PMID 38817600, 2024). "FCM analysis also revealed that administration of the anti-CTLA-4 Ab increased CD4+ T cell infiltration into the tumor." (PMID 39106430, 2024). "Strategies to tailor inhibitory receptor disruption in tumor-specific cellular products have been proposed to overcome these limitations, but are mainly focused on PD-1- or CTLA-4- disrupted cells tested in short-term anti-tumor responses." (PMID 38510235, 2024). "Since the 16 Gy + anti-CTLA4 combination acts directly on priming and activating T cells in TDLNs, and subsequently indirectly on tumor infiltration, this is consistent with having more notable differential gene expression in TDLNs compared to tumors." (PMID 39199612, 2024). "These lymphocytes can infiltrate the matrix and tumor cells to regulate the host’s immune response to tumor cells (Oya, Hayakawa & Koike, 2020), Up-regulated PD-L1 or CTLA-4 expression inhibits these anti-tumor immune responses in some tumor microenvironments." (PMID 39099656, 2024). "Subsequently, in the effector phase, the combined effect of CTLA-4 and PD-L1 inhibitors effectively overcomes the immunosuppressive “brake” exerted by tumor cells, thereby attaining a high level of activation and rapid elimination of tumor cells." (PMID 39038010, 2024). "Inhibiting CTLA-4 leads to increased T-cell activation and more effective immune recognition of tumours." (PMID 38645275, 2024). "Olsenella has been shown to have better antitumor immune effects and anti-CTLA-4 efficacy than Colidextribacter species in a murine tumor model." (PMID 39409735, 2024). "Next, we compared the expression level of PD-1, TIM-3, and CTLA-4 in CD8+ T cells from tumor tissues between PBS treated group and ePAC treated group." (PMID 39269893, 2024). "Cytotoxic T lymphocyte associated protein 4 (CTLA4) is an immune-checkpoint molecule on T cells which interactes with CD80 (B7-1) and CD86 (B7-2) on tumor cells to inhibit the induction phase of the T cell response." (PMID 38439112, 2024).